RPL9 (ribosomal protein L9)
Description:
Component of the large ribosomal subunit. The ribosome is a large ribonucleoprotein complex responsible for the synthesis of proteins in the cell.
Synonyms: L9; uL6; NPC-A-16
Tractability: Small molecule: an approved drug acts on it; a structure with a bound ligand is known; a high-quality ligand is known. PROTAC: ubiquitination databases record sites on it; a small molecule that binds it is known. Other modalities: a drug acting on it is in phase 2 or 3 trials.
Target class: Other cytosolic protein
Gene: Protein-coding gene on chromosome 4 (39,451,747 to 39,458,948, reverse strand). Ensembl gene ENSG00000163682.
Subcellular location: Cytoplasm
Subcellular location (Human Protein Atlas): Cytosol; Endoplasmic reticulum; Nucleoli
Pathways (Reactome):
Metabolism of proteins: Eukaryotic Translation Termination; Formation of a pool of free 40S subunits; GTP hydrolysis and joining of the 60S ribosomal subunit; L13a-mediated translational silencing of Ceruloplasmin expression; PELO:HBS1L and ABCE1 dissociate a ribosome on a non-stop mRNA; Peptide chain elongation; Ribosome Quality Control (RQC) complex extracts and degrades nascent peptide; SRP-dependent cotranslational protein targeting to membrane; ZNF598 and the Ribosome-associated Quality Trigger (RQT) complex dissociate a ribosome stalled on a no-go mRNA
Metabolism of RNA: Major pathway of rRNA processing in the nucleolus and cytosol; Nonsense Mediated Decay (NMD) enhanced by the Exon Junction Complex (EJC); Nonsense Mediated Decay (NMD) independent of the Exon Junction Complex (EJC)
Cellular responses to stimuli: Response of EIF2AK4 (GCN2) to amino acid deficiency
Developmental Biology: Regulation of expression of SLITs and ROBOs
Disease: Viral mRNA Translation
Metabolism: Selenocysteine synthesis
Gene Ontology:
Molecular function: protein binding; structural constituent of ribosome; RNA binding; rRNA binding
Biological process: cytoplasmic translation; negative regulation of myoblast fusion; spermatogenesis; striated muscle contraction; translation
Cellular component: cytoplasm; cytosol; cytosolic large ribosomal subunit; cytosolic ribosome; endoplasmic reticulum; focal adhesion; membrane; nucleolus; nucleus; ribosome
Genetic constraint (gnomAD): Loss-of-function variants: 0 observed, 22.82 expected, observed/expected ratio (o/e) 0, 90% interval 0 to 0.13. The upper end of that interval is the gene's LOEUF score, 0.13, which puts it in group 1 of 6, group 1 being the genes least tolerant of losing a copy. Missense variants: 149 observed, 244.69 expected, observed/expected ratio (o/e) 0.61, 90% interval 0.53 to 0.7. Synonymous variants: 82 observed, 79.25 expected, observed/expected ratio (o/e) 1.03, 90% interval 0.87 to 1.24.
Homologues: Orthologues: chimpanzee RPL9 (100% identical), dog RPL9 (100% identical), macaque RPL9 (100% identical), pig RPL9 (100% identical), rabbit RPL9 (99% identical), rat AABR07026048.1 (94% identical), tropical clawed frog rpl9 (93% identical), zebrafish rpl9 (90% identical), Drosophila melanogaster RpL9 (64% identical), Caenorhabditis elegans rpl-9 (62% identical).
Diseases named in the same sentence as RPL9 in open-access papers:
RPL9 is named in the same sentence as 37 diseases in open-access papers, as found by Europe PMC text mining. Sharing a sentence is not in itself a finding about the gene and the disease. The quoted sentences say what the papers report.
lung carcinoma (3 papers, 2012 to 2023). "The down-regulated RPSA, RPL9, TMSB4X and TUBA1B in normal lung (DDD1) were significantly up-regulated in lung cancer (DDD2)." (PMID 23122428, 2012).
virus infection (3 papers, 2023 to 2025). "This possibility is further corroborated by its chemokine-like role and pro-inflammatory properties that may be inhibited by cationic ribosomal proteins RPL9 in LPS + HMGB1-stimulated TNF-α expression in macrophage-like RAW264.7 cells or in viral infections." (PMID 39494346, 2024).
colon carcinoma (2 papers, 2019 to 2021). "On the other hand, the knockdown of RPL9 by siRNA has been linked to apoptosis in colon cancer cells in vitro and in vivo." (PMID 34873618, 2021). "Knockdown of other RPs such as RPL9 and RPS24 suppressed colon carcinoma cell growth in vitro and human CRC xenografts in nude mice." (PMID 31506518, 2019). "RPL9 KD inactivates Id-1/nuclear factor-κB (NFкB) signaling pathway in HT29 and HCT116 colon cancer cells when compared with the control by phosphorylating IкB, which is known to prevent the translocation of NFкB into the nucleus and the activation of genes that promote cell survival." (PMID 34873618, 2021).
COVID-19 (2 papers, 2021 to 2022). A disease caused by infection with severe acute respiratory syndrome coronavirus 2. "The key genes were involved in 23 KEGG pathways, including COVID-19 (involving RPL9 and RPL31), hepatitis C, influenza A, and ribosome (involving RPL9 and RPL31)." (PMID 35047519, 2021). "There was a positive correlation between the COVID-19-related protein RPL9 and IGF2R." (PMID 35720320, 2022).
rheumatoid arthritis (2 papers, 2022 to 2025). A chronic, systemic autoimmune disorder characterized by inflammation in the synovial membranes and articular surfaces. "Researchers implicate autoantigens, including RPL7, RPL31, RPL14, and RPL9, in the regulation of diseases such as systemic lupus erythematosus, rheumatoid arthritis, and systemic sclerosis." (PMID 35432523, 2022).
acute myeloid leukemia (1 paper, 2025). Acute myeloid leukemia (AML) is a group of neoplasms arising from precursor cells committed to the myeloid cell-line differentiation. "In the RPL9 low-expression group, enrichment was observed in acute myeloid leukemia, axon guidance, tight junctions, γ-mediated phagocytosis, and neural activity-receptor interactions." (PMID 41327671, 2025).
Alzheimer disease (1 paper, 2025). A progressive, neurodegenerative disease characterized by loss of function and death of nerve cells in several areas of the brain leading to loss of cognitive function such as memory and language. "For RPL9 high expression, GSEA pathway scoring highlighted enrichment in Alzheimer disease, Huntington disease, oxidative phosphorylation, Parkinson disease, and ribosomes." (PMID 41327671, 2025).
anemia (1 paper, 2020). A reduction in the number of red blood cells, the amount of hemoglobin, and/or the volume of packed red blood cells. "In clutches of embryos generated from mating two heterozygous rpl9 mutant fish we found that both hetero- and homozygous embryos fail to generate hemoglobin-expressing cells to the same degree as wild type fish, in effect phenocopying the DBA anemia phenotype." (PMID 31799629, 2020).
arrhythmogenic right ventricular cardiomyopathy (1 paper, 2025). "GSVA pathway scoring showed enrichment in arrhythmogenic right ventricular cardiomyopathy, tight junctions, and calcium signaling pathway in the RPL9 high-expression group." (PMID 41327671, 2025).
asthma (1 paper, 2018). "There were common genes between these two study groups, where five genes were up-regulated (ATP5E, BRK1, KCNJ6, RNASEH2C, and RPL9) and one gene (RAB5B) was down-regulated in patients with mild and severe asthma compared with normal individuals." (PMID 30038057, 2018).
bladder cancer (1 paper, 2025). "Collectively, these results demonstrate that HDAC2-mediated delactylation at the K17 site of DHX15 promotes bladder cancer progression, at least in part, by modulating the alternative splicing and downregulating the mature RPL9 transcript." (PMID 41408324, 2025).
male infertility (1 paper, 2023). The inability of the male to effect fertilization of an ovum after a specified period of unprotected intercourse. "The gene RPL9 has been identified as differentially expressed in idiopathic male infertility patients, suggesting that it may play a vital role in male fertility." (PMID 37485336, 2023).
systemic vasculitis (1 paper, 2023). "Ribosomal-related genes such as RPL31 and RPL9 may be implicated in the pathogenesis of systemic vasculitis, which is thought to be uncontrolled genetics that promotes Takayasu arteritis through controlling ribosome pathways." (PMID 38275601, 2023).
type I diabetes (1 paper, 2025). "Meanwhile, the RPL9 low-expression group exhibited enrichment in type I diabetes, protein export, and terpene backbone biosynthesis." (PMID 41327671, 2025).
cancer (8 papers, 2017 to 2025). A tumor composed of atypical neoplastic, often pleomorphic cells that invade other tissues. "Various translation regulators such as eIF4B, ABCE1 and 4E-BP1, or ribosomal proteins, for example RPL29 or RPL9 which have been linked to malignant PCa and other cancers, were found in low abundance in VCaPER." (PMID 36348939, 2022). "In order to determine if the uL6 (RPL9) p.Leu20Pro variant that is linked to cancer also reveals translational fidelity defects, we measured frameshifting and stop codon readthrough in two different assays with dual luciferase reporter vectors." (PMID 31799629, 2020). "We recognize that in the absence of a mouse model it is difficult for us to state definitively that the cancers found in individuals P2 and P3 are directly linked to the RPL9 p.Leu20Pro variant." (PMID 31799629, 2020). "This paradox also applies for mammalian cells: in two independently induced murine cancers, uL6/RPL9 and uL24/RPL26 encoding genes behave as tumor suppressors, whose mutation or loss promotes tumor progression." (PMID 29674660, 2018). "We propose a genotype:phenotype model for RPL9 whereby variants that drive the reduction of uL6 are sufficient to drive DBA but not cancer, in contrast to variants that impair translational fidelity." (PMID 31799629, 2020). "However, the rpl9 heterozygous line is reported to be a non-tumor prone line, suggesting that at least in zebrafish models the mere reduction of rpl9 mRNA is insufficient to drive cancer." (PMID 31799629, 2020). "In the cancer, cell death, and cellular function network, 19 mRNAs and 19 proteins were differentially expressed, including MYC, PSMB9, and RPL9." (PMID 40700094, 2025). "RPL9, or ribosomal protein L (ENSG00000163682), may also contribute to the classification of cancer subtypes and normal control based on the liquid biopsy results." (PMID 29152097, 2017).
tumor (8 papers, 2018 to 2025). "Exome sequencing of tumor and germ line DNA from a family with multiple cancer incidences (P2 and P3) brought to light a missense p.Leu20Pro variant in uL6 (RPL9) that is predicted to be damaging." (PMID 31799629, 2020). "For example, upregulation of expression of ribosomal proteins uL6 (gene RPL9), eL15 (RPL15), and eL39 (RPL39) is associated with increased tumor growth and metastasis in some cancers." (PMID 33990576, 2021). "Ribosomal proteins RPL9 and RPL14 not only play essential roles in translation but also impact the cell cycle and apoptosis, indicating their broader implications in tumor biology." (PMID 40936684, 2025). "coli), RPLP0 (tumor progression, invasion, metastasis), RPS5, RPL9, RPS14, RPS2, RPL3, and RPL23." (PMID 34445327, 2021).
infection (6 papers, 2008 to 2025). The state of being infected such as from the introduction of a foreign agent such as serum, vaccine, antigenic substance or organism. "In the early stages of infection, P induces the translocation of Rpl9 from the nucleus to the cytoplasm and interacts with this ribosomal component." (PMID 34217155, 2021).
metabolic disease (1 paper, 2021). A congenital disorder (due to inherited enzyme abnormality) or acquired (due to failure of a metabolically important organ) disorder resulting from an abnormal metabolic process. "Taken together, RPL9 is a promising candidate gene, and future studies are warranted for understanding the exact role of ribosomal proteins in whole blood and skeletal muscle in metabolic diseases." (PMID 34714849, 2021).
RPL9 also shares sentences with these, for which no sentence is quoted: pancreatic cancer (2 papers); autoimmune disease (1); Autoimmunity (1); co-infection (1); diabetes (1); esophageal squamous cell carcinoma (1); glioma (1); HCMV infection (1); hepatitis C (1); Huntington disease (1); lupus erythematosus (1); lymphoma (1); myocardial infarction (1); Parkinson disease (1); prostate carcinoma (1); systemic immune disorders (1); systemic lupus erythematosus (1); systemic sclerosis (1); Takayasu arteritis (1).